ENSG00000273287 (novel transcript)
Gene: Long non-coding RNA gene on chromosome 22 (45,254,431 to 45,269,169, reverse strand). Ensembl gene ENSG00000273287.
Gene Ontology:
Biological process: SRP-dependent cotranslational protein targeting to membrane, signal sequence recognition
Cellular component: signal recognition particle, endoplasmic reticulum targeting